TARP (TCR gamma alternate reading frame protein )
Gene: Protein-coding gene on chromosome 7 (38,259,643 to 38,273,636, reverse strand). Ensembl gene ENSG00000289746.
Diseases named in the same sentence as TARP in open-access papers:
TARP is named in the same sentence as 25 diseases in open-access papers, as found by Europe PMC text mining. Sharing a sentence is not in itself a finding about the gene and the disease. The quoted sentences say what the papers report.
Chlamydia infection (4 papers, 2014 to 2018). "It has previously been shown that the interaction between TarP and vinculin is required for Chlamydia infection." (PMID 29710402, 2018). "In the majority of cases (>85%), FAK recruitment in TarP-FL- or LD2-expressing cells was found to be transient following a similar profile to that observed during Chlamydia infection." (PMID 25193659, 2014). "Interestingly, the recruitment of vinculin observed during Chlamydia infection was due to a C-terminal VBD within TarP." (PMID 26649283, 2015).
chlamydial infection (4 papers, 2013 to 2020). "All TarP orthologs studied contain a proline-rich domain that mediates TarP oligomerization, a property required for the actin nucleation activity of C. trachomatis TarP and likely crucial for chlamydial infection." (PMID 30629647, 2019). "However, until recently the genetic intractability of chlamydia has precluded determining whether TarP influences the ARP2/3 complex during infection." (PMID 32946535, 2020). "In addition further immunoreactive proteins could be identified such as the homologues of CPAF (CAB712), MIP (CAB080), TARP (CAB167), and PMPD (CAB776); all of them were also discussed as virulence associated factors in other chlamydial infections." (PMID 24260366, 2013).
prostate carcinoma (3 papers, 2012 to 2018). A carcinoma that arises from epithelial cells of the prostate gland. "Further characterizing FABP5 and TARP, they are rearranged in ERG0 samples, which means that these two genes could be used to define distinct group of prostate cancer." (PMID 22811706, 2012).
breast carcinoma (2 papers, 2012 to 2016). "We have previously identified a novel TCR against an HLA-A2-restricted peptide from the prostate and breast cancer-associated antigen TARP and in this study, we have further characterized its interaction and binding to HLA-A2+ targets cells." (PMID 27411667, 2016). "Several naturally generated HLA-A*0201-restricted TARP-peptides which stimulated PCa and breast cancer cell-reactive CTLs in vitro were identified." (PMID 24213236, 2012). "Nonetheless, we believe that the TARP-TCR is an attractive candidate for immunotherapy development for prostate and/or breast cancer." (PMID 27411667, 2016).
trachoma (2 papers, 2016 to 2019). "All sequences were phylogenetically within the T2-trachoma clade and contained ompA, tarP and trpA sequences typical of classical ocular strains." (PMID 31685017, 2019).
campomelic dysplasia (1 paper, 2026). "These genes are associated with recognizable syndromes such as (acampomelic) campomelic dysplasia (SOX9), cerebro‐costo‐mandibular syndrome (SNRPB), SATB2‐associated syndrome (Glass syndrome, SATB2), Catel‐Manzke syndrome (TGDS), TARP syndrome (RBM10), and Stickler syndrome (COL2A1, COL11A1)." (PMID 41077824, 2026).
cleft palate (1 paper, 2012). Cleft palate is a fissure type embryopathy that affects the soft and hard palate to varying degrees. "Finally, deep sequencing of exons on the X chromosome identified RBM10 as the gene causing TARP (MIM 311900), a syndromic form of cleft palate." (PMID 22723972, 2012).
Infertility (1 paper, 2019). "This is in concordance with the study of Graspeuntner et al20 that also found a significant higher level of IgG antibodies targeting chlamydial antigens MOMP, OMP2, CPAF and HSP60, but not TARP in infertile women." (PMID 30629310, 2019).
keratosis (1 paper, 2024). A skin disorder consisting of hypertrophy of the stratum corneum of the skin. "For expanded gene families, we found three genes were associated with skeletal development and/or bone density (HNRNPH1, LIN28A, and TARP) and two genes (FTH1 and KDSR) were related to keratosis." (PMID 39092175, 2024).
leukemia (1 paper, 2021). A malignant (clonal) hematologic disorder, involving hematopoietic stem cells and characterized by the presence of primitive or atypical myeloid or lymphoid cells in the bone marrow and the blood. "Moreover, overexpression of an alternative TARP transcript is specific to AML, being absent in other types of leukemia, such as B-ALL and CML cells." (PMID 34572745, 2021).
osteoporosis (1 paper, 2020). A condition of reduced bone mass, with decreased cortical thickness and a decrease in the number and size of the trabeculae of cancellous bone (but normal chemical composition), resulting in increased fracture incidence. "Meanwhile, to investigate the protective effect of Corilagin on OVX‐induced osteoporosis in histological level, we evaluated distal femur via using haematoxylin and eosin staining (H&E staining), Masson staining and TARP staining." (PMID 32681612, 2020).
prostate tumor (1 paper, 2013). "Twenty-five genes and other transcripts were differentially expressed in the HER2 comparison (21 increased and 4 decreased) including TCRgamma alternative reading frame protein (TARP; 8.74 log2 fold-change; P = 2.31E-04) which is a breast and prostate tumor-associated antigen." (PMID 24324792, 2013).
renal fibrosis (1 paper, 2023). A final common manifestation of a wide variety of chronic kidney diseases characterized by glomerulosclerosis and tubulointerstitial fibrosis. "DOCK2, SLC1A3, SOX9, and TARP were identified as potential diagnostic genes for renal fibrosis, and the most relevant immune cells were identified." (PMID 37359552, 2023). "We also found the expression of DOCK2, SLC1A3, SOX9, and TARP were higher in blood of renal fibrosis patients than healthy individuals." (PMID 37359552, 2023). "Four candidate genes namely DOCK2, SLC1A3, SOX9 and TARP were identified as biomarkers of renal fibrosis, with the area under the ROC curve (AUC) values higher than 0.75." (PMID 37359552, 2023). "The expression levels of DOCK2, SLC1A3, SOX9, and TARP were higher in the renal fibrosis group than in the control group." (PMID 37359552, 2023).
infection (16 papers, 2014 to 2025). The state of being infected such as from the introduction of a foreign agent such as serum, vaccine, antigenic substance or organism. "Suboptimal invasion was reversed by the infection of the TarP-deficient strain that has been complemented with a plasmid-encoded TarP derivative lacking either the PRD (TarPΔPRD) or ABD (TarPΔABD)." (PMID 40131835, 2025). "We present evidence here that supports a working model whereby TmeA associates with the infection synapse formed between the host cell and an invading EB and initiates Arp2/3-mediated actin polymerization independently of TarP." (PMID 33468693, 2021). "The Cpn TarP family member CPn0572 and Ctr TarP share the same actin nucleation activity in vitro and show a similar actin-recruiting activity early in infection in vivo." (PMID 39099397, 2024). "The earliest known chlamydial effector, Ctr TarP is T3SS-translocated into the host cell cytosol within the first 5 min post infection, where it is directly involved in actin polymerization." (PMID 39099397, 2024). "In contrast, S. aureus shifts towards TarS glycosylation at the expense of TarM/TarP WTA glycosylation during in vivo murine infection models and under high salt conditions." (PMID 36748528, 2022). "(i) They should be expressed at mid-to-late stages of the preceding infection cycle, and stored within the EB in preparation for secretion early in the next infection (like adhesins and early effectors like TarP)." (PMID 33194804, 2020). "Consistent with this idea is the continuous presence of the protein throughout infection as well as the induction of a second wave of tarP transcript." (PMID 32843479, 2020). "The candidate type III effector TarP, which localized to focal adhesions during infection and when expressed ectopically, was sufficient to mimic both the reorganization and blebbistatin-resistant phenotypes." (PMID 32843479, 2020). "We next looked at one of the earliest event that occurs upon infection, i.e. tyrosine phosphorylation of host proteins and of at least two effectors, TarP and TepP." (PMID 29868501, 2018). "Vinculin is a key player in the regulation of FA dynamics 42 and cell:cell junctions 43, and the capacity of TarP VBS1 to uncouple vinculin‐mediated cytoskeletal connections during infection is therefore likely to have significant biological implications." (PMID 29710402, 2018). "TarP phosphorylation was detectable as early as 5 min post infection whereas TepP phosphorylation occurred only between 5 and 15 min post infection, indicating that TarP injection occurs first." (PMID 28620586, 2017). "An important aspect of our EPEC/TirM-based experimental model was that it enabled the functional evaluation of TarP at the plasma membrane, where it functions during infection." (PMID 25193659, 2014). "The chlamydial type III effector TarP has been implicated in the invasion process during infection of nonphagocytic cells." (PMID 32843479, 2020). "We identified an infection-dependent change to host cells (FA stability, FA reorganization, and restricted cell motility), a type III effector (TarP) responsible, the relevant target (FAs) of the effector, and an initial mechanism (vinculin dependence)." (PMID 32843479, 2020). "We next asked whether immunolocalization of CT695 resembled that reported for TarP and CT694 during infection." (PMID 26258949, 2015). "Intriguingly, the presence of tarP was strongly associated with the absence of the alternative GT gene tarM, raising the possibility that tarM-mediated WTA modification might interfere with infection by tarP phages." (PMID 36386695, 2022). "However, tarM does not interfere with infection by tarP phages." (PMID 36386695, 2022).
tumor (7 papers, 2014 to 2023). "We also found that several genes, including TYROBP, CD1C, KIR2DL3, CD3G, and TARP, were significantly highly expressed in patients with a high tumor mutational burden." (PMID 35204406, 2022). "ZDHHC11B has been described as an oncogene that promotes cell proliferation, while TARP also promotes tumor cell invasion." (PMID 35562926, 2022). "The purpose of this study was to investigate the difference in target recognition between T-cells with a virus-directed TCR (pp65-specific) and tumor self antigen-directed TCR (TARP-specific) using both established and novel analyses methods." (PMID 27411667, 2016). "A Phase 1 clinical trial showed that TARP peptide vaccination slows PSA doubling time and tumor growth rate in Stage D0 PCa patients with biochemical PSA recurrence (NCT00972309)." (PMID 34988553, 2021). "The PSCA-CAR T cells efficiently killed PSCA-expressing tumor cells from the three donors evaluated, but did not kill TARP-expressing tumor cells." (PMID 24438073, 2014).
cancer (3 papers, 2016 to 2025). A tumor composed of atypical neoplastic, often pleomorphic cells that invade other tissues. "We have in the past cloned a T-cell receptor (TCR) that recognizes an HLA-A2 (MHC class I)-restricted peptide from the prostate and breast cancer- associated antigen TARP." (PMID 27411667, 2016). "We have cloned two TCRs, one TCR recognizes an HLA-A2-restricted peptides from the prostate and breast cancer-associated antigen TARP and in this paper one TCR recognizing an HLA-A2-restricted peptide from the cytomegalovirus (CMV) pp65 antigen." (PMID 27411667, 2016).
TARP also shares sentences with these, for which no sentence is quoted: atrial septal defect (1 paper); Catel-Manzke syndrome (1); Cerebro-costo-mandibular syndrome (1); COVID-19 (1); Glass syndrome (1); melanoma (1); Stickler syndrome (1); Talipes equinovarus (1); TARP syndrome (1).